RPGR (retinitis pigmentosa GTPase regulator)
Description:
Acts as a guanine-nucleotide releasing factor (GEF) for RAB8A and RAB37 by promoting the conversion of inactive RAB-GDP to the active form RAB-GTP. GEF activity towards RAB8A may facilitate ciliary trafficking by modulating ciliary intracellular localization of RAB8A. GEF activity towards RAB37 maintains autophagic homeostasis and retinal function (By similarity). Involved in photoreceptor integrity (By similarity). May control cilia formation by regulating actin stress filaments and cell contractility. May be involved in microtubule organization and regulation of transport in primary cilia. May play a critical role in spermatogenesis and in intraflagellar transport processes (By similarity).
Synonyms: RP3; XLRP3; CORDX1; COD1; CRD; PCDX; RP15; orf15
Tractability: PROTAC: ubiquitination databases record sites on it; its protein half-life has been measured.
Gene: Protein-coding gene on chromosome X (38,269,163 to 38,327,544, reverse strand). Ensembl gene ENSG00000156313.
Subcellular location: Cytoplasm, cytoskeleton, flagellum axoneme; Golgi apparatus; Cell projection, cilium; Cytoplasm, cytoskeleton, microtubule organizing center, centrosome (Isoform 6); Cytoplasm, cytoskeleton, cilium basal body; Cytoplasm, cytoskeleton, cilium axoneme
Subcellular location (Human Protein Atlas): Golgi apparatus; Primary cilium; Cytosol; End piece; Mid piece; Mitochondria; Principal piece
Gene Ontology:
Molecular function: guanyl-nucleotide exchange factor activity; protein binding; RNA binding; ubiquitin protein ligase activity
Biological process: cilium assembly; protein localization to non-motile cilium; visual perception; eye photoreceptor cell development; intracellular protein transport; intraciliary transport; positive regulation of autophagy; protein ubiquitination; ubiquitin-dependent protein catabolic process
Cellular component: centrosome; cilium; Golgi apparatus; photoreceptor outer segment; ciliary basal body; photoreceptor connecting cilium; sperm flagellum; axoneme; photoreceptor cell cilium
Gene-disease validity (ClinGen):
ClinGen rates the evidence that RPGR causes each of these diseases.
RPGR-related retinopathy (X-linked): Definitive. A retinopathy caused by a variant in the X-linked gene, RPGR.
Homologues: Orthologues: chimpanzee RPGR (58% identical), macaque RPGR (55% identical), dog RPGR (49% identical), rat Rpgr (40% identical), mouse Rpgr (39% identical), zebrafish rpgrb (33% identical), zebrafish rpgra (30% identical), tropical clawed frog RPGR (29% identical), Caenorhabditis elegans ran-3 (9% identical), Drosophila melanogaster Rcc1 (8% identical), Drosophila melanogaster CG7420 (8% identical). Paralogues in human: RCBTB1 (11% identical), RCBTB2 (11% identical), HERC1 (11% identical), RCC2 (11% identical), ALS2 (10% identical), SERGEF (9% identical), RCC1 (9% identical), RCC1L (8% identical), RCCD1 (5% identical).
Diseases named in the same sentence as RPGR in open-access papers:
RPGR is named in the same sentence as 89 diseases in open-access papers, as found by Europe PMC text mining. Sharing a sentence is not in itself a finding about the gene and the disease. The quoted sentences say what the papers report.
retinitis pigmentosa (59 papers, 2009 to 2026). Retinitis pigmentosa (RP) is an inherited retinal dystrophy leading to progressive loss of the photoreceptors and retinal pigment epithelium and resulting in blindness usually after several decades. "Retinitis pigmentosa GTPase regulator (RPGR) variants affect both photoreceptor sensory cilia and airway motile cilia, leading to retinitis pigmentosa (RP) and primary ciliary dyskinesia (PCD), respectively." (PMID 41915430, 2026). "LLVA has been shown to enable the earlier detection of disease changes (specifically central retinal sensitivity changes) in choroideremia and retinitis pigmentosa GTPase regulator (RPGR)‐associated retinitis pigmentosa (RP) than standard VA." (PMID 40454673, 2025). "Pathogenic variants in RPGR result in different retinal disorders; these are most commonly retinitis pigmentosa (RP) (70–90%) and less frequently cone dystrophy (COD) (7%) or cone-rod dystrophy (CORD) (6–23%)." (PMID 36835250, 2023). "Males hemizygous for a RPGR mutation often are affected by Retinitis Pigmentosa (RP), whereas female mutation carriers only occasionally present with severe RP phenotypes." (PMID 37541846, 2023). "This study shows that skewed X-inactivation modulates the occurrence of Retinitis Pigmentosa in female carriers of RPGR mutations." (PMID 37541846, 2023). "RPGR encodes the GTPase regulator in retinitis pigmentosa, and its mutation is linked to severe multisystem diseases with strong retinal involvement of photoreceptor neurons." (PMID 37427104, 2023). "The goal of the study was to explore the spectrum of pathogenic variants in the RPGR gene in a group of male Polish patients with a retinitis pigmentosa (RP) phenotype." (PMID 37895299, 2023). "Retinal organoids derived from iPSCs with RPGR gene mutation from retinitis pigmentosa patients not only recapitulated the pathogenesis but also provided proof-of-concept evidence for targeted gene therapy by correction of RPGR mutations." (PMID 35902878, 2022). "X-linked retinitis pigmentosa (XLRP), a rare form of retinitis pigmentosa (RP), is predominantly caused by mutations in the retinitis pigmentosa GTPase regulator (RPGR) gene." (PMID 34659350, 2021). "Correction of retinitis pigmentosa GTPase regulator (RPGR) mutations in iPSCs followed by the generation of retinal organoids proved to be a valuable approach for testing new potential therapies in retinitis pigmentosa." (PMID 33800815, 2021). "Our data expand the landscape of pathogenic variants in RPGR, thereby increasing the genetic diagnostic rate in retinitis pigmentosa and allowing patients harboring the analyzed variants to be enrolled in clinical trials." (PMID 33467000, 2021). "The photoreceptor outer segment is a specialized primary cilium while the retinal pigment epithelium is a ciliated monolayer epithelium, and variants in a number of ciliary proteins, including RPGR, cause retinitis pigmentosa." (PMID 33584830, 2021). "Mutations in the retinitis pigmentosa GTPase regulator (RPGR) gene result in PCD phenotypes with an associated retinitis pigmentosa in humans and mouse models." (PMID 32704025, 2020). "Mutations affecting the Retinitis Pigmentosa GTPase Regulator (RPGR) gene are the commonest cause of X-linked and recessive retinitis pigmentosa (RP), accounting for 10%–20% of all cases of RP." (PMID 31487940, 2019). "Mutations in RPGR (retinitis pigmentosa GTPase regulator) cause the degeneration of the retina (retinitis pigmentosa)." (PMID 31835861, 2019). "Whole exome sequencing in two PRA-affected Weimaraner dogs identified a large deletion comprising the first four exons of the X-linked retinitis pigmentosa GTPase regulator (RPGR) gene known to be involved in human retinitis pigmentosa and canine PRA." (PMID 27398221, 2016).
retinitis pigmentosa (continued). "For example, X-linked RPGR mutations can clinically manifest as forms of retinitis pigmentosa where peripheral retina is affected early and macula is generally spared, or also can manifest as macular degeneration." (PMID 24599007, 2014). "Earlier reports have suggested that there is significant interfamilial variability in the XLRP phenotype and different RPGR mutations can cause divergent retinitis pigmentosa phenotypes." (PMID 20806050, 2010). "Genetic defects in the retinitis pigmentosa GTPase regulator (RPGR) gene cause retinitis pigmentosa and defects in RPGRIP1 cause LCA." (PMID 19223988, 2009). "Indeed, Patient 46 presents GJB2-associated HL and RPGR-associated retinitis pigmentosa while Patient 50 is affected by WFS1-related HL and pseudoxanthoma elasticum due to an ABCC6 mutation." (PMID 36979683, 2023). "Finally, several phenotypic changes associated with retinitis pigmentosa were corrected with the use of CRISPR Cas9 mediated editing of retinitis pigmentosa 3 GTPase regulator (RPGR) in 3D retinal organoid model." (PMID 32671050, 2020). "The occurrence of ‘coverage gaps’ with conventional exome sequencing and their subsequent targeting by ACE is illustrated in RPGR, a gene in which over 300 mutations are implicated in retinitis pigmentosa; and CFTR, a gene in which >1,000 mutations are associated with cystic fibrosis." (PMID 26269718, 2015). "The resulting dendrogram captures some of the known phenotypic similarities in IRDs such as Stargardt phenocopy genes (ABCA4, PRHP2 and PROM1), retinitis pigmentosa genes (RPGR and USH2A) and achromatopsia genes (CNGA3 and CNGB3)." (PMID 40567353, 2025). "Pathogenic variants in the RPGR gene are a known cause of X-linked retinal dystrophy in male patients, which also includes X-linked cone and rod dystrophy 1 (OMIM #304020) and retinitis pigmentosa 3 (OMIM #300029)." (PMID 39495751, 2024). "CRISPR/Cas9 was applied to correct mutations in RPGR and CEP290 associated with Retinitis Pigmentosa and Leber congenital amaurosis." (PMID 39439625, 2024). "RPGR mutations reduce the GDP/GTP exchange activity and disrupt cilia function and are associated with retinitis pigmentosa." (PMID 38548946, 2024). "Genetic characteristics and a long-term clinical follow-up of 18 Slovenian retinitis pigmentosa GTPase regulator (RPGR) patients from 10 families with retinitis pigmentosa (RP) or cone/cone-rod dystrophy (COD/CORD) are reported." (PMID 36835250, 2023). "Sequencing of the low-complexity ORF15 exon of RPGR, a gene correlated with retinitis pigmentosa and cone dystrophy, is difficult to achieve with NGS and Sanger sequencing." (PMID 38069202, 2023). "Retinitis pigmentosa, another IRD often caused by frameshift mutations in the OFR15 exon of RPGR (retinitis pigmentosa GTPase regulator) gene." (PMID 37545694, 2023). "Up to five genes causing X-linked RP have been identified, with RPGR (retinitis pigmentosa GTPase regulator) and RP2 (retinitis pigmentosa 2) accounting for the majority of cases." (PMID 36498452, 2022). "It was also published as a candidate for the retinitis pigmentosa RP3 locus, although this link was later disproven when RPGR (retinitis pigmentosa GTPase regulator) was identified as the causative gene for this phenotype." (PMID 35006274, 2022). "Beispiele hierfür sind die autosomal-dominante okkulte Makuladystrophie (RP1L1-Gen) und die X‐chromosomale Retinitis pigmentosa (RPGR-Gen) – Letztere auch bei heterozygoten, weiblichen Merkmalsträgerinnen (Konduktorinnen)." (PMID 32458067, 2021). "RPGR exon ORF15 variants are one of the most frequent causes for inherited retinal disorders (IRDs), in particular retinitis pigmentosa." (PMID 32679846, 2020).
retinitis pigmentosa (continued). "Gene therapy for RPGR-related retinitis pigmentosa (e.g., NCT: 03116113) is currently in clinical trials for males." (PMID 30567410, 2018). "The incomplete penetrance of XLRP phenotype of other RPGR carriers suggested that annual follow up examinations checking symptoms of Retinitis Pigmentosa (RP) is warranted." (PMID 30245926, 2018). "RPGR is a gene related to retinitis pigmentosa (RP) and cone dystrophy." (PMID 38069202, 2023). "Retinitis pigmentosa was the most represented phenotype (56%), followed by cone dystrophy (11%) and Leber congenital amaurosis (7%), while ABCA4 was the most frequently mutated gene (18%), followed by USH2A (9%) and RPGR (5%)." (PMID 35836572, 2022). "We aimed to validate the effect of non-canonical splice site variants in the RPGR gene in five patients from four families diagnosed with retinitis pigmentosa." (PMID 33467000, 2021). "Two members of a large X-linked Retinitis Pigmentosa pedigree clinically presented with choroideremia and tested negative for the segregating RPGR variant found in other affected members of this pedigree." (PMID 31963381, 2020). "With RPGR gene therapy currently undergoing clinical trials for males, there must be the consideration for therapeutic intervention in females who also suffer from the severe phenotype of retinitis pigmentosa." (PMID 30567410, 2018). "NME3 could provide the substrate for cilium-associated G-proteins such as RPGR (retinitis pigmentosa), GPR48 (polycystic kidneys), RanGDP/GTP, and ARL6 (retinitis pigmentosa and BBS)." (PMID 30111592, 2018). "Also, retinal organoids serve to model X-linked juvenile retinoschisis, and late-onset retinitis pigmentosa and recapitulate the pathogenesis of retinitis pigmentosa, allowing for CRISPR-Cas9-mediated correction of RPGR mutation to reverse ciliopathy and photoreceptor loss." (PMID 34299287, 2021).
retinal degeneration (32 papers, 2010 to 2026). Degeneration of the retina. "RPGR function requires glutamylation by tubulin tyrosine ligase-like 5 (TTLL5) whose mutation is also linked to severe forms of retinal degeneration." (PMID 41941273, 2026). "In summary, our findings highlight the therapeutic relevance of the human-specific isoform RPGRs14/15 and identify ripasudil as a promising candidate for treating RPGR-associated retinal degeneration." (PMID 41323795, 2025). "This study provides a possible mechanistic explanation for RPE atrophy and retinal degeneration in patients with RPGR mutations." (PMID 41288322, 2025). "Loss of RPGR in mice models and humans results in progressive retinal degeneration characterized by photoreceptor dysfunction." (PMID 41288322, 2025). "Mutations in genes such as RHO (Rhodopsin), RP1, and RPGR (retinitis pigmentosa GTPase regulator) have been among the most described, leading to a disruption in key photoreceptor functions with subsequent retinal degeneration." (PMID 40731809, 2025). "This pilot study investigates the potential pathogenic role of G-quadruplex (G4) structures in RPGR-associated retinal degeneration, starting from a case of suspected X-linked form affected family." (PMID 38699732, 2024). "Heterozygous CEP290 variants in RPGR-knock-out male mice have been described to cause a worse retinal degeneration progression, being a genetic modifier of XLRP severity." (PMID 38534367, 2024). "The specific pathogenic mechanisms underlying RPGR-related retinal degeneration are not fully understood." (PMID 37893030, 2023). "The loss of RPGR function in human and mouse models causes retinal degeneration with the mislocalization of rod and cone opsin, the reduction of ERG function at early ages, and the progressive loss of photoreceptor cells with aging." (PMID 37351277, 2023). "Mutations in the RPGR gene can affect the normal function of the RPGR protein, leading to retinal degeneration in XLRP." (PMID 37893030, 2023). "Mutations in the gene for Retinitis Pigmentosa GTPase Regulator (RPGR) cause the X-linked form of inherited retinal degeneration, and the majority are frameshift mutations in a highly repetitive, purine-rich region of RPGR known as the OFR15 exon." (PMID 34257417, 2022). "Retinal degeneration has also been reported in dogs carrying naturally occurring mutations in the RPGR or RPGRIP1 gene." (PMID 29796181, 2018). "In contrast to CEP290, RPGR mutations primarily cause retinal degeneration (with a few leading to syndromic phenotypes)." (PMID 23351659, 2012). "Mutations in RPGR account for over 70% of X-linked retinitis pigmentosa (XlRP), characterized by retinal degeneration and eventual blindness." (PMID 21857984, 2011). "We recently showed that mutations in NPHP8, which alter its interaction with RPGR, act as modifiers of the expressivity of the retinal degeneration phenotype in ciliopathy patients." (PMID 20664800, 2010). "Due to the importance of these pathways in photoreceptor development and survival, mutations in RPGR might disrupt the interactions and lead to retinal degeneration." (PMID 36650468, 2023). "In addition, the fundus changes vary widely among patients with RPGR variants, including gray-white fundal spots, tessellated fundus, retinal degeneration to macular degeneration in males and female carriers." (PMID 34745198, 2021). "Retinal degeneration 9 (rd9) mice carry a mutation in the retina specific “Retinitis Pigmentosa GTPase Regulator (RPGR)” Open Reading Frame (ORF) 15 gene, located on the X chromosome and represent a rare model of X-linked Retinitis Pigmentosa (XLRP), a common and severe form of retinal degeneration." (PMID 31607844, 2019). "Perturbations in the assembly of RPGR complexes are associated with retinal degeneration." (PMID 20664800, 2010).
retinal degeneration (continued). "NPHP4 interacts with retinitis GTPase regulator (RPGR) and RPGR-interacting protein 1 (RPGRIP1), potentially establishing a connection to the development of retinal degeneration in patients with an NPHP4 mutation." (PMID 40427560, 2025). "Our study reveals a novel pathological mechanism of RPGR-related retinal degeneration and provides potential therapeutic targets centered on RPE lysosomal lipid metabolic modulation." (PMID 41288322, 2025). "We have reported a similar phenotypic spectrum for RPGR-affected carriers, ranging from sector RP to severe early-onset retinal degeneration." (PMID 37977507, 2024). "Our findings provide novel insights into the formation of G4-quadruplex structures within the RPGR gene and their potential impacts on DNA replication and transcription in the molecular pathogenesis of RPGR-related retinal degeneration." (PMID 38699732, 2024). "Female carriers of RPGR mutations in two pedigrees (RF.VI123.0514 and RF.VI153.0216) developed retinal degeneration phenotype." (PMID 34662339, 2021). "In mouse, deletion of RPGR results in a slower retinal degeneration, while loss of RPGRIP1 leads to an early onset retinal degeneration with abnormal development of outer segments." (PMID 29796181, 2018). "In the context of gene therapy and correction, CRISPR/Cas9 technology has also been explored for in vivo restoration of RPGR expression (the gene responsible for X-linked retinitis pigmentosa, XLRP) in animal models to treat a severe form of inherited retinal degeneration." (PMID 41157282, 2025). "TTLL5 pathogenic mutations even lead to the absence of glutamylation on RPGR, compromising its function and leading to a retinal degeneration phenotype." (PMID 35656327, 2022). "Mice lacking RPGR were crossed to a line with a mutation in the gene encoding centrosomal protein 290 (CEP290), resulting in double homozygotes with a more severe and rapid progression of retinal degeneration, indicating a genetic interaction between RPGR and CEP29016." (PMID 32704025, 2020). "Less deleterious/hypomorphic alleles in these same genes may manifest as refractive error without retinal degeneration (e.g., female carriers of pathogenic RPGR variants)." (PMID 41465105, 2025). "According to the literature, it is still not clear whether all the loss of function RPGR variants result in retinal degeneration through the loss of protein function or gain a new one." (PMID 33805381, 2021). "RPGR gene canine models (XLPRA1 and XLPRA2) have been treated with subretinal AAV2/5 full-length human RPGRex1-ORF15, with beneficial rescue of photoreceptor dysfunction to halt retinal degeneration." (PMID 31739639, 2019).